EGFR (epidermal growth factor receptor)
Diseases named in the same sentence as EGFR in open-access papers (continued):
Sharing a sentence is not in itself a finding about the gene and the disease.
diabetes (152 papers, 2009 to 2026). "Increased EGFR in T1D patients is associated with prolonged diabetes duration and heightened DKD risk." (PMID 40661817, 2025). "Meanwhile, EGFR inhibitors show promise in preventing or treating corneal damage caused by diabetes." (PMID 40391004, 2025). "Consistent with our study, impaired p-EGFR signaling pathway is directly associated with the progression and development of diabetes." (PMID 41189666, 2025). "Nevertheless, the underlying mechanism through which Anxa2 regulated EGFR signaling in diabetes‐related CIRI remains elusive." (PMID 39912333, 2025). "After adjusting for sex, age, BMI, hyperlipidemia, hypertension, diabetes, brain metastases, and radiotherapy, the EGFR‐TKI group had an almost 2.78‐fold higher relative risk of increased WMH load compared to non‐EGFR‐TKI." (PMID 38054663, 2023). "Studies have shown that loss of function of tyrosine protein kinase in EGFR pathway or abnormal activity or cell localization of key factors in the pathway can lead to the occurrence of tumor, diabetes, and immune deficiency." (PMID 37996895, 2023). "Mice expressing constitutively-active EGFR in the pancreas are protected against the development of beta cell toxin-induced diabetes in that their beta cell loss is inhibited." (PMID 37233668, 2023). "The activation of EGFR signaling has been implicated in numerous pathophysiological processes, including diabetes." (PMID 37374078, 2023). "Perturbations in EGFR expression and signalling are implicated in several pathophysiological conditions including cancer and diabetes." (PMID 34408653, 2021). "Further, EGFR signaling has been implicated in a spectrum of neurometabolic conditions, such as metabolic syndrome, diabetes, AD, cancer, and cardiorespiratory function." (PMID 29551980, 2018). "An interesting finding of the in vivo studies was the association of EGFR phosphorylation with diabetes-induced 11β-HSD1 pathway and downstream cardiac dysfunction." (PMID 29221204, 2017). "End-organ nephropathy and renal damage are commonly observed in diabetes that in some cases can be linked to increased EGFR expression and activity as well as oxidative stress." (PMID 26167903, 2015). "Because insulin and EGF stimulate TRPM6 function, patients with diabetes mellitus type 2 or users of EGFR inhibitors are at risk to develop hypomagnesemia." (PMID 25774985, 2015). "In summary, we have demonstrated that EGFR inhibitors prevent upregulation of pathways that are implicated in the sodium and water retention seen in patients with diabetes mellitus and exacerbated by the use of PPARγ agonists." (PMID 23533381, 2013). "This is not an unexpected finding as we showed above that diabetes is associated with reduced EGFR/erbB2 heterodimers and thus appear to be important signaling partners in cardiac function including following I/R injury." (PMID 22720029, 2012). "Signaling studies confirmed that diabetes is associated with a reduction in EGFR and erbB2 phosphorylation at multiple tyrosine residues that appear to be important signalling cues for downstream effectors such as ERK1/2, p38MAP kinase and AKT." (PMID 22720029, 2012). "In addition to EGFR/ErbBs mediating diabetes-induced vascular dysfunction, EGFR has also been directly linked to diabetes-induced vascular remodeling." (PMID 39234105, 2024). "Furthermore, the EGFR pathway has the potential to be broadly important in the context of T1D, as EGFR has been identified as a susceptibility gene for diabetic neuropathy and diabetes associated cardiac dysfunction." (PMID 37903947, 2023). "Increased EGFR contributes to insulin resistance and correlates with a higher risk of developing diabetes, and the use of TKI inhibitors in most cases led to an arrest of diabetes development, normalization of glycemia, and in extreme cases even to diabetes re-emission." (PMID 35054822, 2022).
diabetes (continued). "Hence, EGFR/ErbBs are key regulators of many cellular homeostatic functions and their dysregulation is associated with several pathological functions including diabetes-induced cardiovascular dysfunction." (PMID 34408653, 2021). "In addition, inhibition of EGFR prevents the majority of the changes in gene expression within the rat mesenteric vasculature associated with streptozocin-induced diabetes." (PMID 24132149, 2013). "Abnormal myogenic tone associated with diabetes is mediated in part via EGFR signaling." (PMID 24132149, 2013). "Inhibiting EGFR expression or activity has been shown to slow the progression of diabetic kidney injury, suggesting that directly targeting EGFR or its associated signaling pathways may be an effective strategy for preventing progressive kidney damage caused by diabetes." (PMID 40141782, 2025). "Research shows that EGFR may be related to heart injury caused by diabetes." (PMID 37063954, 2023). "Further, simple correction of hyperglycemia per se also does not completely prevent development of vascular complications in patients with diabetes implying that other factors associated with the diabetic state could induce ErbB2/EGFR/ERK1/2/ROCK signaling- a possibility that needs further study." (PMID 23826343, 2013). "After birth, tissue-specific attenuation of EGFR signaling in the β-cell using a dominant negative EGFR (EGFR-DN) that lacks 40% of tyrosine kinase activity leads to a failure of postnatal β-cell proliferation and islet mass expansion, resulting in insulin-deficient diabetes by two weeks of life." (PMID 20807437, 2010). "EGFR is predominantly expressed within the islets and is critical for β-cell development, function, and proliferation in diabetes." (PMID 41189666, 2025). "Acetylcorynoline, which targets EGFR/MAPK signaling, presents an additional layer of therapeutic promise, particularly in reducing neuroinflammation associated with diabetes." (PMID 41155161, 2025). "Increased EGF and EGFR staining is observed in the retinas of patients with PDR, and inhibition of the EGFR reduces macula oedema, angiogenesis, and inflammation in mouse models of diabetes and diabetic retinopathy." (PMID 39433211, 2025). "A selective EGFR inhibitor (gefitinib) decreased oxidative stress and attenuated diabetes-induced myocardial collagen deposition and fibrosis in STZ-induced diabetic mice." (PMID 39140033, 2024). "Use of selective inhibitors of EGFR and/other ErbBs were able to reverse multiple diabetes-induced signaling changes including oxidative stress signaling, inflammatory markers, nitric oxide (NO) synthase (eNOS) activity and NO production in the vasculature." (PMID 39234105, 2024). "Mechanistically, upregulation of EGFR signaling appears to be a key early vascular change induced by diabetes as EGFR inhibition was able to correct more that 90% of all diabetes-induced gene expressions in the diabetic vasculature." (PMID 39234105, 2024). "Upregulation of EGFR, and other ErbBs, has been reported in conditions of hyperglycemia and/or diabetes." (PMID 39234105, 2024). "Chronic EGFR inhibition resulted in a significant reduction in diabetes-induced blood vessel intima and media thickening and correction in vascular hyper-responsiveness through EGFR-ERK1/2-ROCK dependent pathway." (PMID 39234105, 2024). "The potentially beneficial action of EGFR inhibitors in diabetes, and specifically in DN, requires further confirmation and validation in large scale clinical studies in human subjects." (PMID 39234105, 2024). "Proinflammatory cytokines have been found to decrease with diabetes treatment, and EGFR inhibition has also been demonstrated to reduce the production of these cytokines." (PMID 38916734, 2024). "The regulation by ACE2 also regulates the EGF transactivation in diabetes and phosphorylation of EGFR in kidney cells." (PMID 37084657, 2023). "ACE2 also regulates the EGF transactivation in diabetes and phosphorylation of EGFR in kidney cells." (PMID 37084657, 2023).
diabetes (continued). "EGFR is a tyrosine kinase involved in cell proliferation, division, mitosis, and the occurrence of cancer and diabetes." (PMID 37996895, 2023). "It is found that diabetes induces the phosphorylation of EGFR and Akt, increases the level of cardiac ROS, and eventually leads to cardiac morphological changes, consisting of cardiac hypertrophy, apoptosis and fibrosis." (PMID 37063954, 2023). "In animal models of diabetes and cultured cells treated with high glucose, the level of phosphorylation of renal EGFR was significantly increased." (PMID 37789280, 2023). "Proximal tubule hypertrophy is an early response seen with the onset of diabetes, and in a streptozotocin model of type I diabetes, either erlotinib or selective proximal tubule deletion of EGFR expression reduced this early kidney hypertrophy." (PMID 36359813, 2022). "Although the main goal is currently cancer therapy, and their action is based on ERBB2/EGFR inhibition, it has been noticed (in clinical observations) that they additionally alleviate the symptoms of diabetes." (PMID 35054822, 2022). "Another previous study indicated that EGFR has a critical role in progressing STZ-induced diabetes in rat models." (PMID 35956419, 2022). "In another study, the inhibition of miR-133b resulted in accelerated wound healing in diabetes-impaired wound healing through the restoration of epidermal growth factor receptor (EGFR) expression and angiogenesis." (PMID 35954282, 2022). "Diabetes-induced increased expression of EGFR and their ligands and subsequent EGFR activation have been previously reported both in in vivo models and in cultured renal proximal tubule epithelial cells." (PMID 36359813, 2022). "Other previous studies indicated that EGFR has a critical role in the progression of STZ-induced diabetes in rat models." (PMID 35956419, 2022). "cardiovascular complications - implying that EGFR/ErbB receptor activation and subsequent NOX-mediated ROS/oxidative stress are critical in mediating vascular dysfunction associated with diabetes." (PMID 34408653, 2021). "Collectively, these results implied that EGFR/ErbB2-ERK1/2-ROCK pathway is an important mediator of diabetes-induced vascular dysfunction." (PMID 34408653, 2021). "EGFR plays a significant role in the progression of diabetic kidney disease (DKD) evident by significantly increased level of phosphorylated EGFR levels in animal models of diabetes mellitus and in cultured cells treated with high glucose." (PMID 34535145, 2021). "Several studies have now shown that EGFR inhibition leads to a reduction in NOX activity in models of diabetes-induced." (PMID 34408653, 2021). "Although there are no clinical trials designed for treatment of human DKD by targeting EGFR, there are two case reports about the application of EGFR inhibitor erlotinib in diabetes." (PMID 33574751, 2020). "In STZ-induced diabetes models, EGFR inhibition markedly reduced renal oxidative stress and endoplasmic reticulum stress (ERS), and attenuated renal fibrosis and apoptosis." (PMID 33574751, 2020). "Renal EGFR phosphorylation levels were significantly increased in animal models of diabetes mellitus and in cultured cells treated with high glucose." (PMID 33574751, 2020). "In the past decades, much attention has been paid on application of tyrosine kinase inhibitors to treat diabetes, including EGFR inhibitors in animal models." (PMID 33574751, 2020). "Inhibition of EGFR tyrosine kinase activity with erlotinib attenuates renal damage in an experimental animal model of diabetes, partly by inhibition of ER stress." (PMID 33067928, 2020). "EGFR can be abnormally activated during diabetes or atherosclerosis and the enhanced EGFR activity with downstream endoplasmic reticulum (ER) stress in cardiovascular system has been reported in T2DM." (PMID 32851081, 2020).
diabetes (continued). "Thus, our work implied that treatment of diabetes-induced vascular dysfunction- a precursor to the development of disease associated neuropathy- with EGFR inhibitors might also be potentially useful in preventing or at least delaying diabetic neuropathy and attenuating neuropathic pain." (PMID 32547536, 2020). "In a diabetes model with eNOS knockout, inhibition of EGFR attenuated albuminuria, glomerulosclerosis and tubulointerstitial fibrosis, along with a decreased urinary excretion of F2-isoprostane, a marker of oxidative stress." (PMID 33574751, 2020). "In this regard, we were the first to show that increased EGFR signaling was a critical mediator of diabetes-induced microvascular dysfunction." (PMID 32547536, 2020). "On the converse, findings from another study examining murine mesangial cells demonstrated a beneficial effect of EGFR inhibition against cell death mediated by EGFR which preceded development of diabetes." (PMID 32956382, 2020). "Multiple effects on insulin sensitivity, diabetic complications together with the anticancer efficacy point to the high potential of targeting both the MST and EGFR/ErbB2 axes for diabetes therapy." (PMID 31815004, 2019). "We have recently shown, in both asthma and diabetes disease models, in which EGFR activity is enhanced, that inhibition of Src kinase reduces EGFR transactivation and ameliorates the disease features." (PMID 31675376, 2019). "In a model of streptozotocin-induced diabetes, the genetic blockade of EGFR or pharmacological inhibition using erlotinib showed a downregulation of phospho-AKT, CTGF, and AREG expression compared to that in diabetic mice." (PMID 30670929, 2018). "EGFR plays a key role in the development of cardiac hypertrophy and it is also activated in diabetes." (PMID 29221204, 2017). "The EGFR signaling is activated in early diabetes and plays an important role in kidney hypertrophy and fibrosis." (PMID 28427241, 2017). "When some EGFR inhibitors were given to the patients suffering from both cancer and diabetes mellitus, it not only treated cancer but also improved diabetes mellitus." (PMID 28053990, 2016). "We have previously shown the diabetes and/or hyperglycemia induces upregulation of EGFR and ErbB2 expression and phosphorylation that leads to vascular dysfunction via pathways involving ERK1/2, p38 MAPK and ROCKs." (PMID 26536590, 2015). "Diabetes resulted in a net increased EGFR phosphorylation in the diabetic kidney compared to control animals." (PMID 26167903, 2015). "In contrast to EGFR and ErbB2 receptors, the effect of diabetes or high glucose on the phosphorylation of other members of the ErbB family of receptor tyrosine kinases is not well characterized." (PMID 26536590, 2015). "In summary, inhibition of diabetes-elevated miR-146a in organ-cultured diabetic corneas normalized epithelial wound healing and activated signaling molecules, EGFR and p38." (PMID 25490205, 2014). "We and others have previously demonstrated that EGFR is upregulated in the kidneys of animals with experimentally induced diabetes and high glucose regulates its transactivation." (PMID 23533381, 2013). "In a very recent study that was attempting to understand how insulin paradoxically temporally increases retinal edema in diabetes mellitus, it was found that EGFR signaling increases vascular leakage in diabetic mice." (PMID 24132149, 2013). "Ang II, and Aldosterone levels appear raised in diabetes and are also known transactivators of EGFR, and possibly ErbB2, via src and MMP-dependent mechanisms." (PMID 23826343, 2013). "We have further observed delayed wound healing in normal corneas upon overexpression of diabetes-upregulated proteinases that was accompanied by reduced expression of activated EGFR and Akt." (PMID 24376808, 2013).
diabetes (continued). "Here, we examined the role of ErbB2 (HER2/Neu), a transmembrane receptor tyrosine kinase of the ErbB/EGFR (epidermal growth factor receptor) family, in mediating diabetes-induced vascular dysfunction in an experimental model of type 1 diabetes." (PMID 23826343, 2013). "In conclusion, this study has identified a novel signaling mechanism leading to diabetes-induced vascular dysfunction that involves activation of ErbB2 receptor tyrosine kinase, heterodimer formation with EGFR and downstream signaling via ERK1/2 and ROCK." (PMID 23826343, 2013). "At doses that have previously been shown to prevent diabetes-induced vascular dysfunction, AG1478 administered chronically or acutely, also attenuted the diabetes-induced changes in total and/or phosphorylated EGFR, ROCK and ERK1/2." (PMID 23826343, 2013). "EGFR signalling is a key initiator of multiple signalling pathways in the development of diabetes-induced vascular dysfunction and renal pathology." (PMID 23533381, 2013). "This suggests that inhibiting EGFR activation may be beneficial, not only in preventing sodium and water retention generally observed in patients with diabetic nephropathy, but also in limiting sodium and water retention associated with the use of PPARγ agonists in patients with diabetes mellitus." (PMID 23533381, 2013). "EGFR/erbB2 signaling is an important cardiac survival pathway whose activation, particularly in diabetes, ischemia or following treatment with drugs that inhibit this cascade, significantly improves cardiac function." (PMID 22720029, 2012). "Diabetic hearts treated with Losartan exhibited a lower EGFR phosphorylation compared to untreated diabetes following I/R." (PMID 22720029, 2012). "Losartan treatment improved cardiac function in diabetes but also impaired EGFR phosphorylation in diabetic heart." (PMID 22720029, 2012). "This study characterized the effects of diabetes and/or ischemia on epidermal growth factor receptor, EGFR, and/or erbB2 signaling pathways on cardiac function." (PMID 22720029, 2012). "EGFR signaling has been highlighted directly or indirectly in a spectrum of neurometabolic conditions, for example, metabolic syndrome, diabetes, Alzheimer's disease, cancer, and cardiorespiratory function." (PMID 22754566, 2012). "Several studies have also shown that the number of surface EGFR molecules is decreased in hepatocytes isolated from the streptozotocin-induced diabetes rat model." (PMID 22952896, 2012). "We found that chronic inhibition of either EGFR or erbB2 receptor signaling generally exacerbated recovery from ischemia-reperfusion injury of hearts isolated from normal and diabetes." (PMID 22720029, 2012). "Further, consistent with ARBs known inhibition of Angiotensin II-mediated transactivation of EGFR, diabetic hearts treated with Losartan reduced EGFR phosphorylation compared to untreated diabetes following I/R." (PMID 22720029, 2012). "Further, EGF-mediated activation of EGFR/erbB2/AKT signaling in the hearts via modulation of FOXO3a activity appears to be a critical survival pathway in preventing diabetes-mediated cardiac dysfunction." (PMID 22720029, 2012). "Consistent with this, we showed that diabetes-led to an attenuation in EGFR/erbB2/AKT pathway that was further attenuated upon exposure of hearts to ischemia and correlated with a worsening recovery of cardiac function following I/R." (PMID 22720029, 2012). "(b) The second network demonstrates novel interactions between GAPDH and inflammatory and proliferation candidate genes i.e., SUMO4 and EGFR indicating a new link between obesity and diabetes." (PMID 19997558, 2009). "In the context of diabetes pathogenesis, SRC, FYN, and EGFR are significantly implicated in the development of vascular complications, such as diabetic kidney injury, and have been reported to prevent/improve diabetic nephropathy and other diabetic-related kidney injuries." (PMID 41011980, 2025).